IL6 (interleukin 6)
Diseases named in the same sentence as IL6 in open-access papers (continued):
Sharing a sentence is not in itself a finding about the gene and the disease.
Sepsis (continued). "In a prospective multicenter study, plasma from 21 infants with clinical sepsis was analyzed for biomarkers, including IL-1Ra, IL-6, circulating intercellular adhesion molecule-1 (clCAM-1) and CRP, in a ten-day period over a septic episode and compared to 20 infants with no infection." (PMID 36769133, 2023). "Additionally, LPS caused elevated levels of TNF-α, IL-1β, IL-6, and MCP-1 in the supernatant of HK-2 cells, showing that there was increased inflammation in our cellular models of sepsis." (PMID 37085762, 2023). "Inflammatory cytokines are linked to the progression of sepsis by causing an excessive inflammatory response, and HMGB1 functions as a proinflammatory molecule to increase the secretion of inflammatory cytokines such as TNF-α, IL-6 and IL-1β." (PMID 38026444, 2023). "The objective of this systematic review was to determine whether PCT, CRP, IL-6, and sCD14 are independent prognostic factors for predicting mortality in critically ill adults with sepsis." (PMID 37537680, 2023). "A more recent study assessed vaginal IL-6 concentration daily and demonstrated a significant difference in vaginal IL-6 concentration between pregnancies with signs of fetal inflammation and/or early onset sepsis compared to controls." (PMID 38001923, 2023). "However, the subsequent study of sepsis patients with IL-6 concentrations >1000 pg/mL who were randomly assigned to receive afeliomab or placebo was terminated early after the primary efficacy endpoint was estimated not to be met due to interim analysis." (PMID 38114466, 2023). "We found that ACT001 treatment reduced IL-6 expression on mRNA and protein levels in sepsis mice." (PMID 38094883, 2023). "TNF‐α and IL‐6 are the first cytokines activated and released during the acute infectious period, initiate the SIRS response to sepsis, and are key to the deterioration of patients with septic shock, while PCT is a diagnostic and prognostic marker of sepsis." (PMID 37102655, 2023). "CD137 can activate different cells and induce the expression of IL-6 by these cells, and the positive association of IL-6 and sCD137 indicates that the immunosuppressive effects of sCD137 are less effective in SIRS/sepsis patients." (PMID 38139346, 2023). "Furthermore, the nuclear translocation of NF-κB activates the transcription of several inflammatory cytokines, including TNF-α and IL-6, and eventually triggers cytokine storms during sepsis." (PMID 38343439, 2023). "However, the use of non-selective sympatholytic drugs including clonidine and dexmedetomidine attenuated the increase in plasma IL-6 and enhanced the increase in IL-10 levels in ovine sepsis, likely due to activation of anti-inflammatory cholinergic pathways." (PMID 37535121, 2023). "As various inflammatory cytokines are affecting each other in cytokine release syndrome, we hypothesized whether increase of IL-6 cytokine could be a main trigger to the severe hyperdynamic state in sepsis or that of other cytokines could." (PMID 37007795, 2023). "In addition, sepsis patients also show higher plasma levels of pro-inflammatory cytokines, including IL-6, IFN-γ, and TNF-α." (PMID 36671034, 2023). "In contrast to CHO-L, LAN-L significantly suppressed sepsis-induced elevation of IL-6, KC, and sTNFRI, suggesting that LAN-carrying liposomes (LAN-L) conferred protection against lethal sepsis partly by attenuating sepsis-induced tissue injury and dysregulated inflammation." (PMID 37239992, 2023). "Additionally, the concordance of MR effect estimates between cisCRP and cisIL6R genetic variants provides confidence in our primary analysis and strongly supports the role of IL-6 signalling in sepsis." (PMID 36716318, 2023). "HBO2 treatment has been shown to reduce proinflammatory cytokines such as IL-1, IL-6, and TNF-α both in vitro and in vivo, and HBO2 treatment was associated with a decrease in IL-6 and G-CSF in plasma from Group A-Streptococcus NSTI sepsis patients." (PMID 37627293, 2023).
Sepsis (continued). "IL-6 is a well-known sepsis biomarker, and its levels correlate with the severity of sepsis." (PMID 37391846, 2023). "However, the Ticagrelor-treated group showed significantly decreased expression of the inflammatory markers IL-6 and IL-1β compared to the sepsis group." (PMID 37675176, 2023). "IL-6 has been evaluated as a biomarker in sepsis, septic shock, and community-acquired pneumonia." (PMID 37733154, 2023). "Additionally, the diagnostic criteria used, such as the clinical sepsis definition or culture-proven definition, can impact the interpretation of IL-6’s sensitivity in diagnosing sepsis." (PMID 38255366, 2023). "Exosomes derived from adipose stem cells could reduce the expression of IL-1β, TNF-α and IL-6 in macrophages during sepsis while also downregulating M1 markers (iNOS and CD86) expression." (PMID 37635258, 2023). "Considering these clinical and experimental results, they speculated an essential role of IL-6 signaling in endothelial dysfunction in sepsis and cytokine release syndrome." (PMID 36622466, 2023). "The Mg‐Tob motor conveyed satisfactory anti‐inflammation protection by neutralizing multiple pro‐inflammatory cytokines involving TNF‐α, IL‐6 and IL‐1β both in vitro and in vivo, which ensured it as an excellent candidate to prevent the development of highly heterogeneous inflammation in sepsis." (PMID 37818787, 2023). "It is important to note that IL-6 signalling did not account for all of the observed risk of sepsis with reduced small HDL particle count in either our observational analysis (adjusting for CRP) or our genetic analyses." (PMID 37814277, 2023). "Likewise, the levels of IL-6 (P = 0.0347), sE-selectin (P = 0.0060), and sVCAM-1 (P < 0.0001) were significantly higher in patients with sepsis than in healthy controls." (PMID 37414769, 2023). "IL-6 release generally follows that of TNF-α and is also an important inflammatory cytokine; several studies have shown that higher plasma levels of IL-6 are more likely to cause sepsis patients to die faster." (PMID 36675101, 2023). "Interleukin-6 has been used in sepsis diagnosis, but cut-off values are missing." (PMID 36216867, 2023). "However, in another study, the diagnostic accuracy of MR-proADM for sepsis detection was inferior to clinically used biomarkers (CRP, PCT, and IL-6), and the combination of MR-proADM with any of these markers did not improve diagnostic accuracy." (PMID 37626802, 2023). "In serums of patients with severe infections or sepsis, levels of IL-6 exceed 1000 pg/ml." (PMID 35144683, 2022). "IL-1 and IL-6 are also important inflammatory cytokines in sepsis." (PMID 36185646, 2022). "This systematic review and meta-analysis showed that dexmedetomidine sedation in sepsis patients could significantly decrease mortality and IL-6 and TNF-α levels at 24 h compared with other sedatives." (PMID 36029410, 2022). "It concludes that the accentuated levels of TNF-alpha and IL-6 may be the inciting agent for the hepatocellular dysregulation in the early stage of sepsis." (PMID 35282512, 2022). "The decreased levels of TNF-α and IL-6 revealed the advantage therapy role of GF9 on sepsis." (PMID 36110326, 2022). "In contrast, isorhamnetin is known to inhibit TNF-α and IL-6 in a model of E. coli-induced sepsis." (PMID 36361685, 2022). "In severe sepsis, the concentration of IL-6 can reach 100–1000 ng/mL." (PMID 35463642, 2022). "The expression of IL-6, TNFα and other sepsis biomarkers is in fact regulated by miRNAs." (PMID 36291031, 2022). "IL-6 levels were found to be fivefold higher in septic shock patients, and 2.7-fold higher in sepsis patients, compared with patients with infection (319.00 pg/mL [105.1–1870.00] and 166.70 pg/mL [56.98–1033.00] vs 61.81 pg/mL [21.56–370.5]; p < 0.01 and p < 0.05)." (PMID 36536294, 2022).
Sepsis (continued). "In addition, we measured the mRNA levels of the inflammatory cytokine IL‐6, which is important in the pathobiology of sepsis, tumor necrosis factor alpha (TNF‐α), and the chemokine MCP‐1, at 24 h after CLP." (PMID 34355516, 2022). "This is the first study we are aware of that demonstrates an association between cord blood IL-6 and leptin in appropriate for gestational age infants without sepsis." (PMID 35197933, 2022). "The cytokine storm, a key feature of sepsis that has been linked to increased risk of mortality, is characterised by a life-threatening systemic inflammation caused by high circulating levels of the proinflammatory cytokines TNF-α, IL-6, and IL-1β." (PMID 35625756, 2022). "Furthermore, IL-6 and IL-10 elevation at sepsis onset was associated with an increased risk of NPMODS, proving the efficacy of Th1/Th2 cytokines in predicting sepsis prognosis." (PMID 36544765, 2022). "High levels of IL-6 are produced in sepsis patients, which remains high for more than a week." (PMID 35962414, 2022). "Our results indicated that the serum IL-6 level in sepsis mice rose markedly." (PMID 35197852, 2022). "Among all Th1/Th2 cytokines, IL-6 and IL-10 were particularly elevated in G- sepsis patients." (PMID 36544765, 2022). "These compounds exhibit protective effect on cardiac, lung, liver, and kidney against sepsis-induced acute organ damage, and several studies showed the ability of these phytochemicals to modulate cytokines related to inflammation such as IL-6, IL-1β, and TNF-α." (PMID 36588685, 2022). "Overall, these results suggest IL-6 and H2S may serve as early markers of inflammation during E. coli- and K. pneumoniae-induced sepsis." (PMID 35955767, 2022). "Furthermore, a randomized controlled trial in septicemia showed decreased inflammation by reducing IL-6 levels." (PMID 35882835, 2022). "Cepharanthine, an alkaloid isolated from Stephania cepharantha Hayata, demonstrated effectiveness in managing systemic inflammatory response syndromes including sepsis by inhibiting the rise in LPS-induced cytokine levels (IL-6, TNF-α, and nitrate/nitrite levels) in rat serum." (PMID 36588685, 2022). "IL-6 concentration is recognized as a marker of sepsis with high specificity." (PMID 35563475, 2022). "Furthermore, studies have shown that the proinflammatory cytokines interleukin-6 and tumor necrosis factor-alpha can be used as markers to diagnose sepsis." (PMID 35991069, 2022). "In addition, the deletion of ferritin heavy chain ameliorates the inflammatory burden in the model of sepsis, including reduction of IL-1β, IL-6, IL-12, and IFN-γ and improves survival." (PMID 36357401, 2022). "The average concentration of each protein was significantly higher in patients with sepsis than in normal controls (P < 0.0001, IL-3; P = 0.0001, IL-6; P < 0.0001, PCT; unpaired two-sided t test), which supported the potential use of these markers for sepsis detection." (PMID 36129990, 2022). "IL-6 levels are also elevated in sepsis and directly correlate with mortality." (PMID 35548445, 2022). "CRP, PCT and also IL-6, IL-8 and sFAS levels were significantly higher in patients with sepsis." (PMID 35550043, 2022). "Increased IL-6 levels can lead to an acute phase response (inducing expression of C-reactive protein and fibrinogen, thereby enhancing localized infection) and is correlated with the severity of sepsis." (PMID 36060742, 2022). "Similar to TNF-α, the crucial roles of IL-1β and IL-6 in sepsis are also established." (PMID 35337084, 2022). "Under inflammatory conditions TNF and IL-6 demonstrate some functional redundancy: for example, they both mediate inflammatory response during sepsis, and may act as immunometabolic transmitters." (PMID 35408882, 2022). "In previous studies, CRP, IL6, and lactate could be used as biomarkers to evaluate the diagnosis and prognosis of sepsis severity in humans." (PMID 35205254, 2022).
Sepsis (continued). "Moreover, the inflammatory cytokines of TNF-α and IL-6 were significantly higher in sepsis patients than in control (p < 0.01)." (PMID 36110326, 2022). "We detected the expression levels of TNF-α, IL-1β, IL-6, and IL-10 in sera and BALF of septic mice using ELISA, and the results indicated that Fer-1 reduced the upregulation of the expression levels of inflammatory factors caused by sepsis in mice (P < 0.05)." (PMID 35910848, 2022). "Early in sepsis, Kupffer cells play an essential role in the removal of bacteria and endotoxins through the release of proinflammatory cytokines such as interleukin (IL)-1β, IL-6, IL-18, and tumor necrosis factor-alpha (TNF-α)." (PMID 36120368, 2022). "Given that B cells were shown to promote early production of proinflammatory cytokines such as IL-6 during sepsis in a type I IFN dependent manner, we next investigated if LPS pretreatment improved tissue damage control by dampening B cell driven inflammatory responses." (PMID 36178806, 2022). "In line with this, the experimental results from ELISA analysis underlined that sepsis might lead to inflammatory response by elevating the levels of TNF-α, IL-6, IL-1β and IL-18." (PMID 35264055, 2022). "Therefore, MZ B cells can play a dual regulatory role in the inflammatory response to sepsis by producing pro-inflammatory factors such as IL-6 and anti-inflammatory factors such as IL-10." (PMID 36425582, 2022). "IL-6 levels are significantly elevated up to 48 h prior to the onset of clinical sepsis." (PMID 35345614, 2022). "As known for severe sepsis, increased levels of CPK, BUN, and IL-6 were detected in the sera of mice, indicating skeletal muscle degradation, kidney injury, and systemic inflammation, respectively, during the acute phase of moderate sepsis." (PMID 36148245, 2022). "However, plasma levels of IL-10, IL-6, and IL-8 were significantly increased in sepsis compared to HCs and w/o sepsis patients." (PMID 35720398, 2022). "A blockade of IL-6 or TNF-α was confirmed to increase the survival of patients with sepsis." (PMID 35283837, 2022). "Compared with G+ sepsis, IL-6 and IL-10 were significantly elevated in G- sepsis (p < 0.05)." (PMID 36544765, 2022). "Sepsis-related novel biomarkers, including IL-8, IL-6, and angiopoietin-2, were included in the final models, but could also be substituted by other features without significant impact on the performance." (PMID 35453552, 2022). "Sepsis is closely associated with the inflammatory response which is associated with elevated blood levels of pro-inflammatory cytokines such as TNF-α, IL-1β and interleukin-6 (IL-6)." (PMID 36613652, 2022). "Interestingly, TNF-α and IL-6 as cytokines involved in endothelial damage, and multiple organ dysfunction syndrome, are often used as biomarkers for sepsis." (PMID 36536294, 2022). "However, “IL-6 IL-10 ratio” was relatively lower in G- sepsis patients with bloodstream infection and ARDS." (PMID 36544765, 2022). "More importantly, “IL-6 IL-10 ratio” could easily reflect the extent of pro-inflammatory and anti-inflammatory status during sepsis, which is crucial in sepsis progression." (PMID 36544765, 2022). "In LPS-induced sepsis, activation of TLR4 causes downstream NF-κB and MAPKs pathways to be activated in a MyD88-dependent manner, thereby enhancing pro-inflammatory cytokines including TNF-α and IL-6." (PMID 36402943, 2022). "In a prospective observational analysis, PTX-3, IL-6, procalcitonin (PCT), and lactate combined showed excellent performance in predicting 28-day all-cause mortality among patients diagnosed with sepsis or septic shock and superior to the Sequential Organ Failure Assessment (SOFA) score." (PMID 34991675, 2022). "However, for patients with progressively deteriorating organ function [new or progressive multiple organ dysfunction syndrome (NPMODS)], differences in IL-6 and IL-10 levels were less significant between G+ and G- sepsis." (PMID 36544765, 2022).
Sepsis (continued). "From our results, oXiris-CHFA treatment initiated in the early stage of sepsis (AKI stage 1) may reduce the levels of proinflammatory factors such as IL-6 more significantly than in the later stage (AKI stage 2–3)." (PMID 36249210, 2022). "The pro-inflammatory cytokine IL-6 also has been used in diagnosing sepsis." (PMID 35615626, 2022). "Furthermore, the levosimendan pretreatment reduced NO, TNF-α, IL-6, and IL-1β, as well as liver enzymes, in the serum of the sepsis rats, suggesting a hepatoprotective effect." (PMID 36551917, 2022). "The incubation of leukocytes with renin induces the production of pro-inflammatory cytokines, including IL-6, and administration of a renin receptor blocker reduced the pro-inflammatory response and increased survival in a rodent model of sepsis induced by cecal ligation and puncture (CLP)." (PMID 36117167, 2022). "In addition, a large number of secretory inflammatory factors such as tumor necrosis factor α (TNF-α) and interleukin-6 (IL-6) are also involved in the sepsis myocardial damage." (PMID 34757596, 2022). "Despite these limitations, these results could help to generate new hypotheses on the prognostic, but also etiological, role of IL-6 and IL-18 in sepsis." (PMID 36189302, 2022). "Compared with the control group and the sham group, the IL-6, IL-β, INF-α protein expression of the hippocampus in the sepsis group was up-regulated (p < 0.05); After administration of the inhibitor echinomycin, the protein expression of IL-6 and TNF-α were decreased." (PMID 36569834, 2022). "At the Fluids time-point, circulating levels of pro-inflammatory cytokines (TNF-α and IL-6) had increased similarly in the two treatment groups in response to sepsis; Anti-inflammatory IL-10 levels were increased in the Ang II group at VP1 compared to baseline." (PMID 36117167, 2022). "Thus, our study indicated that the miR-26a-5p/IL-6 axis can alleviate sepsis-induced acute kidney injury by inhibiting renal inflammation." (PMID 35491874, 2022). "In a previous proteomics study conducted by our group in adult sepsis patients, we proposed a set of 10 proteins (AT-III, CLUS, SAA-1, HO-1, IL-6, IL-18, sCD25, sCD163, sICAM-1 and sFas) that can be considered as a complementary tool for the clinicians in the diagnosis of sepsis." (PMID 35329889, 2022). "Hierarchical clustering analysis showed that resistin and inflammatory cytokines formed a network that includes interleukin (IL)-6, IL-8, IL-10 and monocyte chemotactic protein 1 (MCP-1) in the acute phase of sepsis and burns and that this network is associated with severity and prognosis." (PMID 35784283, 2022). "Previous studies have shown that obeticholic acid, a derivative of chenodeoxycholic acid, can improve bile acid homeostasis; inhibit the expression of TNF-α, IL-6, and IL-1β; and alleviate sepsis-related liver injury, which suggests that bile acids have a protective effect against sepsis." (PMID 35115021, 2022). "Interestingly, a previous study investigated cecal ligation and puncture (CLP) as an experimental sepsis model in mice deficient for IFN-γ and found decreased amounts of macrophage inflammatory protein-2 (MIP-2) and IL-6." (PMID 36361636, 2022). "Thus, our study indicated that the miR-26a-5p/IL-6 axis alleviates sepsis-induced acute kidney injury by inhibiting renal inflammation." (PMID 35491874, 2022). "It causes the release of IL-1 and IL-6, thus enhancing the non-specific immune response to sepsis, burn injury or inhalation injury." (PMID 35054900, 2022). "Medians of IL-6 levels in G+ and G- sepsis groups were 54.24 and 271.37 pg/ml, respectively." (PMID 36544765, 2022). "Subgroup analysis revealed that for sepsis patients characterized by progressive organ dysfunction, levels of IL-6 and IL-10 were less helpful in identifying bacterial Gram types while more strongly correlated with NPMODS but independent of baseline organ dysfunction." (PMID 36544765, 2022).